C6orf47 (chromosome 6 open reading frame 47)
Synonyms: G4; D6S53E; NG34
Tractability: PROTAC: ubiquitination databases record sites on it; its protein half-life has been measured.
Gene: Protein-coding gene on chromosome 6 (31,658,298 to 31,660,778, reverse strand). Ensembl gene ENSG00000204439.
Subcellular location (Human Protein Atlas): Cytosol
Gene Ontology:
Molecular function: protein binding
Genetic constraint (gnomAD): Loss-of-function variants: 2 observed, 10.32 expected, observed/expected ratio (o/e) 0.19, 90% interval 0.078 to 0.61. The upper end of that interval is the gene's LOEUF score, 0.61, which puts it in group 2 of 6, group 1 being the genes least tolerant of losing a copy. Missense variants: 323 observed, 383.79 expected, observed/expected ratio (o/e) 0.84, 90% interval 0.77 to 0.92. Synonymous variants: 149 observed, 170.94 expected, observed/expected ratio (o/e) 0.87, 90% interval 0.76 to 1.
Homologues: Orthologues: pig C6orf47 (81% identical), guinea pig C6orf47 (79% identical), dog C6orf47 (78% identical), rabbit C6orf47 (77% identical), mouse D17H6S53E (76% identical), rat G4 (75% identical).
Diseases named in the same sentence as C6orf47 in open-access papers:
C6orf47 is named in the same sentence as 7 diseases in open-access papers, as found by Europe PMC text mining. Sharing a sentence is not in itself a finding about the gene and the disease. The quoted sentences say what the papers report.
breast carcinoma (1 paper, 2025). "Although the function of C6orf47 in tumor biology has not been fully elucidated, our spatial transcriptome analysis suggests that its expression changes may participate in breast cancer development." (PMID 41275376, 2025).
celiac disease (1 paper, 2017). An autoimmune genetic disorder with an unknown pattern of inheritance that primarily affects the digestive tract. "The strongest independent CD interaction signal corresponded to genes in the HLA class III region, in particular PRRC2A and GPANK1/C6orf47, which are known to contain variants for non-Hodgkin's lymphoma and early menopause, co-morbidities of celiac disease." (PMID 28282431, 2017).
Crohn disease (1 paper, 2020). A gastrointestinal disorder characterized by chronic inflammation involving all layers of the intestinal wall, noncaseating granulomas affecting the intestinal wall and regional lymph nodes, and transmural fibrosis. "Our analysis resulted in five candidate genes corresponding to two of the major IBD subtypes: UBE2L3 and SLC22A4 for Crohn’s Disease and TCF19, C6orf47 and SNAPC4 for Ulcerative Colitis." (PMID 34968289, 2020).
tumor (3 papers, 2013 to 2025). "The expression of many genes like TSC22D4, POLR2J, PPP1R, and C6ORF47 was dependent on the aggressiveness of the tumor." (PMID 27340651, 2013).
C6orf47 also shares sentences with these, for which no sentence is quoted: infection (1 paper); non-Hodgkin lymphoma (1); ulcerative colitis (1).